IL4 (interleukin 4)
Diseases named in the same sentence as IL4 in open-access papers (continued):
Sharing a sentence is not in itself a finding about the gene and the disease.
tumor (continued). "As expected, body weight in the C26 hosts was lower than in C (Day 0: 21.57 ± 1.07 g; 25% reduction), while it remained comparable with Day 0 in tumour‐bearing mice receiving IL4." (PMID 32103619, 2020). "In contrast, Th2 cells, arising from IL-4 stimulation, create IL-4 and IL-10 and favor tumor growth by suppressing the generation of Th1 and CTLs." (PMID 33144870, 2020). "This was associated with increased numbers of CD8+ T-cells in tumors, and reduced the number of CD4+ T-cells, the main source of the Th2 cytokine IL4 which can lead to a pro-tumor advantage." (PMID 32656079, 2020). "In contrast to IL-1β and IL-4, IL-10 overexpression elicits tumor rejection by stimulating cytotoxicity of CD8 (+) T cells by inducing the expression of IFN-γ in CD8 (+) T cells." (PMID 33112542, 2020). "IL-4 is generated by both tumor cells and stromal cells, and IL-4 neutralization resulted in reduced levels of the chemokines CCL2, CCL11, and CXCL5 in the TME." (PMID 33178603, 2020). "At the same time, another Th2 cytokine IL4 increases tumor infiltration with eosinophils and macrophages that can kill tumor cells." (PMID 32582698, 2020). "While both methods lower the total number of macrophages, the macrohpages that remain even with recruitment inhibition are closer to the tumor, where IL-4 levels are highest, which keeps them in the M2 state." (PMID 33362239, 2020). "A possible limitation in the present study is that increased tumour mass occurs when IL4 is administered to C26‐bearing mice." (PMID 32103619, 2020). "During tumor development, an increased expression of IL-4R, IL-4 as well as IL-13 and its high affinity receptor IL-13Rα2 are detected in some epithelial cancers, including CRC." (PMID 33371444, 2020). "We had previously shown the effectiveness of sclareol in reducing the tumor volume, suppressing the regulatory T cells and shifting the cytokine profile with decreasing interleukin-4 (IL-4) and augmenting IFN-γ." (PMID 32922496, 2020). "Analysis of early intra-tumor infiltrates revealed increased numbers of vaccine-elicited B and T clones expressing IL-2, IL-4, and IL-5." (PMID 33266109, 2020). "Together, our results suggest that the reduction in Cdc42 expression in tumor-infiltrating iNKT cells disturbs IL4 polarization and interferes with iNKT cells-DC crosstalk, which contributes to the impaired antitumor Th1 responses mediated by iNKT cells." (PMID 31160756, 2020). "As for the different muscle stem cell populations, the results showed that SC number was lower in C26 hosts administered with IL4 than in untreated tumour‐bearing animals (C26 = 17.1 ± 5.2%, C26 + IL4 = 10.9 ± 2.0%)." (PMID 32103619, 2020). "Th1 lymphocytes exert an antitumor effect by releasing tumor necrosis factor α (TNF-α), and IFN-γ, while Th2 cells mainly produce interleukin (IL) 4 (IL-4) and thereby promote tumor growth by inhibiting the host’s immune system." (PMID 33050416, 2020). "IL-4 inhibits tumor growth by inhibiting angiogenesis and also blocks corneal neovascularization induced by basic fibroblast growth factor." (PMID 32366355, 2020). "IPA analysis suggests that this is likely due to the presence of pro-M2/Th2 cytokines such as IL-4 and IL-13, in the tumor microenvironment." (PMID 32699181, 2020). "Interleukins (IL)-4 and IL-13 are among the immunomodulatory cytokines believed to play a prominent role in tumor immunity." (PMID 32512917, 2020). "While several cytokines have well-established pro-tumor effects (e.g., IL-1, IL-4, IL-6) and can be produced by tumors directly in an autocrine manner, not all cytokines contribute toward pro-tumor processes." (PMID 33597950, 2020). "On the contrary, Th2 cells secrete pro-tumoral cytokines, such as IL-4, IL-5, IL-6, IL-10, and IL-13, which induce anergy in T cells and promote the activities of tumor-promoting macrophages." (PMID 33322132, 2020). "The close relationship between IL-4 and tumor progression has been investigated in several diseases." (PMID 32692308, 2020).
tumor (continued). "In general, CAR-T cells would kill tumor cells accompanied with the release of cytokines, including IL-2, IL-4, IL-6, IFNγ, and TNFα." (PMID 31998790, 2020). "In ESCC, fold-increase in IL-4 protein concentration in tumor was strongly directly correlated with tumor grade." (PMID 32512917, 2020). "The administration of IL4 to the C26 hosts resulted in increased tumour mass that however does not necessarily reflect an increased number of tumour cells." (PMID 32103619, 2020). "Macrophages were generated by either polarizing them in the presence of the M2 cytokines IL4 (M2(IL4)) or IL10 (M2(IL10)) or in the presence of tumor-cell conditioned medium (TAM-like)." (PMID 32438733, 2020). "Neutralizing antibodies to IL-4 have inhibited tumor growth in xenograft models by reducing expression of anti-apoptotic Bcl-xL and Bcl-2." (PMID 32512917, 2020). "The most important MDSC activating mediators are the Transforming Growth Factor (TGF-ß), ligands for toll-like receptors, IL-1β, Interferon (IFN)-γ, and IL-4 which are chiefly originated from activated T cells and tumor stromal cells." (PMID 33133086, 2020). "If that would be the case, it would explain the fact that, even with high concentration of IL-4, the viability of tumor cells decreases, because the sIL-4R would bind IL-4, hence diminishing its concentration in the tumor microenvironment." (PMID 33312693, 2020). "They differentiate from circulating monocytes after migrating into tumor tissue upon stimulation with IL-4, IL-10, or IL-13 and exhibit pro-tumorigenic functions." (PMID 32184778, 2020). "These promising results with ICRs have led to further ICR investigations, such as the novel IL-4 vs. IL-21 ICR (4/21) that promotes Th17-like polarization in CAR T-cells in response to IL-4 in the TME that resulted in improved tumor-clearance in vivo." (PMID 33643299, 2020). "With macrophage depletion, new macrophages enter the environment farther from the tumor where IL-4 levels are lower, allowing some of them to differentiate to the M1 state." (PMID 33362239, 2020). "It enables Th2 to express IL-4 and other cytokines, promotes antibody production, mediates humoral immunity, and suppresses anti-tumor immunity." (PMID 33115513, 2020). "Due to the number of tumor cells, average and maximum IL-4 levels are relatively high while IFN-γ levels are low due to low T cell activation." (PMID 33362239, 2020). "They derive from circulating monocytes and are skewed to the M2 phenotype by tumor-secreted cytokines, like interleukin-4 (IL-4) and macrophage-colony stimulating factor (M-CSF)." (PMID 32069856, 2020). "Our results demonstrated that the level of NMU mRNA in HCC peri- and intra-tumor tissue was positively related to the levels of type-2 cytokine mRNA, including IL-4, IL-10, and IL-13." (PMID 32013887, 2020). "Th2 cytokines, such as tumor-derived IL-4, can help generate M2 macrophages and MDSCs to block tumor-specific CTL activity." (PMID 35310881, 2020). "in their GI track show a lower expression of IL-4 that suppressed the activity of MDSCs on anti-tumor T-cells by downregulating arginase 1 expression." (PMID 33330446, 2020). "Although HT1080 and IL4-MΦ co-cultures were well-mixed, stochastic distributions created diversity in the distance between tumor cells and their closest neighboring MΦ." (PMID 32665556, 2020). "Quantitative analysis of tumor RNA regarding specific cytokines for mast cells recruitment such as IL4 and IL9 confirmed our observations." (PMID 33086657, 2020). "Collectively, we found that M2 polarized BMMs (IL-4-induced, or tumor conditioned media induced) had increased expression of Myc mRNA as compared to M0 or IFNγ-induced M1 macrophages." (PMID 32685002, 2020). "In the immune escape stage, the tumor macroenvironment maintains immunosuppression due to the secretion of many growth factors and cytokines, such as IL-4 and IL-13, by cancer cells." (PMID 32850861, 2020).
tumor (continued). "Paired comparison of IL-4 in adjacent and tumor colonic tissue showed significantly higher protein concentration in tumors but similar expression level of IL4 and IL4Ra transcripts." (PMID 32512917, 2020). "Th2 cells are known to eliminate tumor cells by recruiting tumoricidal eosinophils and macrophages to the tumor microenvironment due to the secretion of IL-4 and IL-13 cytokines." (PMID 32508847, 2020). "The protumor activity of ILC2s is mainly attributed to IL-33-driven IL-4 and IL-13 production from these cells which have been reported to support tumor development and progression." (PMID 33233582, 2020). "Basophils expressing IL-4 present in the tumor draining lymph nodes of patients with PDAC probably contribute to the stabilization of the Th2 phenotype, since their presence correlates with an increased Th2/Th1 ratio in tumors and poor patient survival." (PMID 33022971, 2020). "In previous studies, CD4+ T cells and tumor cells engineered to secrete IL-4 have been shown to have potent antitumor effects." (PMID 31937346, 2020). "We evaluated the plasma concentrations of Th1 (IL-2, IFN-γ, and TNF-α), Th2 (IL-4, IL-5, IL-6, and IL-10), Th9 (IL-9), and Th17 (IL-17A, IL-17F, IL-21, and IL-22) cytokines in tumor-bearing mice by flow cytometry." (PMID 32802733, 2020). "In accordance with the data from APCmin/+ mice, IL-4 has a positive impact on tumor progression in CAC, as shown by the reduced growth of tumors after AOM/DSS treatment in the absence of IL-4." (PMID 33371444, 2020). "Lymphocytes can induce the death of cytotoxic cells, and produce cytokines, such as interleukin-4 and interleukin-12, that inhibit the proliferation and metastasis of tumor cells." (PMID 32833961, 2020). "The higher expression levels of IFN-γ and IL-2 and the lower expression levels of IL-4 in the tumor tissue of DTSP-treated mice suggest that a Th1 immune response but not a Th2 immune response was activated by DTSP treatment." (PMID 32903495, 2020). "This then allows macrophages newly recruited to the tumor site, which enter the simulation at a distance from the tumor and thus far from peak IL-4 levels, to differentiate to M1 and increase the T cell response." (PMID 33362239, 2020). "After IL4-MΦ co-culturing, we imaged tumor cells in contact with MΦ and quantified their EB3 tracks." (PMID 32665556, 2020). "As explained in detail in the methods section, we have constructed a multi-scale agent-based model of the interactions between macrophages, T cells, and tumor cells, along with the cytokines IL-4 and IFN-γ." (PMID 33362239, 2020). "Alternatively, activated macrophages (M2) are stimulated by IL-4 and IL-13 and are involved in tissue repair, suppression of inflammation and tumor progression by secreting the anti-inflammatory cytokines IL-10 and TGF-β." (PMID 32184778, 2020). "M1 macrophages also amplify Th1 responses, providing a positive feedback loop in anti-tumor response, while M2 macrophages (“healing” phenotype) are mainly stimulated by interleukin-4 (IL-4) or IL-13, inclined to facilitate tumor growth and progression." (PMID 32002338, 2020). "On the contrary, CD4+ TH2, producing IL-4, IL-5, and IL-13, generally promote tumor growth and development." (PMID 32235370, 2020). "In this study, in the orthotopic-mice model of HCC, YPF increased the levels of Th1 cytokines (IL-2, IL-12, TNF-α, and IFN-γ), decreased the levels of Th2 cytokines (IL-4, IL-5, IL-10, and IL-13), and increased the Th1/Th2 ratio in tumor and adjacent tissues." (PMID 32351590, 2020). "Our previous research in mice has proven that Vγ4 γδ T cells play a protective role in tumor immunity, whereas Vγ1 γδ T cells suppress this function via interleukin 4 (IL-4) production." (PMID 32695099, 2020). "Although vaccination with both human ESCs and iPSC lines induced significant expansion of tumor-specific IFNγ- and IL-4-producing T cells, only human ESC cells inhibited tumor growth." (PMID 33266109, 2020).
tumor (continued). "This knowledge led us to evaluate the concentration of Th-1 (IFN-γ, IL-2) and Th-2 (IL-10, IL-4) serum cytokines in M-406 bearing CBi/L mice, in the different stages of tumor immunoediting." (PMID 33312693, 2020). "The anti-tumor effect of conventional Th9 cells induced under IL-4 plus TGF-β treatment was dependent on IL-9." (PMID 32508847, 2020). "In terms of tumor activity, elevated Th2 cytokines [interleukin‐4 (IL‐4), IL‐5, and IL‐13)] and decreased Th1 cytokines (IL‐2 and interferon γ (IFN‐γ)—interferon‐γ) suppress effective spontaneous antitumor immunity." (PMID 32485045, 2020). "Upon IL4 treatment, a high number of cytotoxic lymphocytes and type II macrophages were observed with a subsequent increase in necrotic areas of C26 tumours." (PMID 32103619, 2020). "IL4 was reported to promote differentiation, proliferation, and survival of different tumor cells through its interaction with IL4R." (PMID 32181251, 2020). "Tumour-infiltrating CD73+γδ1 T cells express high levels of IL-4, IL-17A, IL-10, GM-CSF and TGF-β, and exert immunosuppressive functions mainly via the adenosine-mediated pathway." (PMID 32345959, 2020). "Tumor cell products (such as IL-10, IL-4, and CCL2) affect the M1/M2 transformation of TAMs, and TAMs, in turn, regulate the biological behavior of tumor cells by secreting small molecular substances." (PMID 32653013, 2020). "Consistently, the immunofluorescence indicated that the borders of necrotic areas in tumours from IL4‐treated C26 hosts were as well positive for F4/80 and CD206." (PMID 32103619, 2020). "This is most likely due to the decrease in IL-4 as tumor cells and M2 macrophages are removed, allowing some of the new macrophages to differentiate into the M1 state." (PMID 33362239, 2020). "It has been well-established that in response to the Th2 cytokines interleukin-4 (IL-4) and interleukin-13 (IL-13), macrophages undergo alternative activation, gaining abilities to support tumor growth and inhibit antitumor immunity." (PMID 33178603, 2020). "Tumor-infiltrating Th2 cells secrete IL-4, which supports the differentiation of tumor-infiltrating monocytes and macrophages into M2-like TAMs (tumor-associated macrophages)." (PMID 31256327, 2020). "IL-4 blockade not only reduced the formation of immunosuppressive M2 macrophages and MDSCs but also increased the function of tumor-specific cytotoxic T cells." (PMID 33255425, 2020). "Blockade of IFN-γ with neutralizing antibodies resulted in slightly high proportion of M1 macrophage compared with that in cryo-thermal eosinophils + tumour-bearing macrophage group, and IL-4 neutralizing reduced it." (PMID 31519961, 2019). "Flow cytometric analysis of freshly prepared tumor cell suspensions revealed increased intracellular ratios of IFN-γ to IL-4 in CD4+ and CD8+ memory T cells, and activation of tumor-associated myeloid cells and microglia with upregulation of HLA-DR and PD-L1." (PMID 30506500, 2019). "In mice with normal immunity, the serum IFN-γ (a Th1 cytokine) level and the tumoral expression of Arg1+ cells (M2 TAMs) were elevated, but the IL-4 (a Th2 cytokine) level and the expression of iNOS+ cells (M1 TAMs) were diminished after tumor inoculation." (PMID 31781219, 2019). "For example, macrophages exposed to IL-4, IL-10, and IL-13 differentiate into the M2 phenotype during tumor progression and secrete IL-4, IL-5, and IL-6 to enhance angiogenesis, immunosuppression, and matrix remodeling." (PMID 31192126, 2019). "In this study, CcR expression induced phosphorylation of STAT5 (part of the native signaling cascade in IL7 signaling) after ligation with tumor-secreted IL4, and restored T cell proliferation in the presence of the cytokine." (PMID 31024832, 2019). "Several gene therapy approaches by our group and others have shown that IL-4 delivery in immunocompetent hosts with malignant gliomas results in a significant impairment of tumor growth and prolonged survival." (PMID 30909395, 2019).
tumor (continued). "M1 macrophages are known to have an important role in the immunoediting phase of early tumor elimination, while in established tumors, Th2 cytokines (IL-4 and IL-13) elicit alternative M2 activation." (PMID 31554173, 2019). "MUC-1-specific CAR T cells have been engineered with a switch receptor containing an IL-4 ectodomain and an IL-7 endodomain to counter the IL-4-rich tumor microenvironment." (PMID 30842774, 2019). "The different phenotype, based on CD44 gene expression in PC3 and DU145 cells, was confirmed by a different response to IL-4, a regulator of basal-like cells showing characteristics of tumor-initiating cells by inducing expression of CD44." (PMID 30754655, 2019). "In one xenograft model, IL-4-producing SMMC-7721 tumor cells were subcutaneously transplanted into immunodeficient mice." (PMID 31379876, 2019). "In contrast, M2 TAMs are activated by the Th2 cytokines like IL-4 and IL-10 and responsible to the expression of IL-10 and arginase, immunosuppression, as well as the promotion of tumor growth." (PMID 31781219, 2019). "The milieu of cells in the tumor microenvironment produces cytokines such as IL-4, IL-10, IL-13, and M-CSF that encourage M2 or immunosuppressive phenotype differentiation." (PMID 30931508, 2019). "TGFβ, IL-4, and IL-10 are anti-inflammatory pleiotropic signaling molecules that are involved in critical functions during tumor promotion and progression." (PMID 31174326, 2019). "Signal transducer and activator of transcription 6 (Stat6) is the main transcription factor of interleukin-4 (IL-4) signaling and its participation in the development of various tumor types has been already reported." (PMID 30353167, 2019). "PSCA CAR T cells that also contained a 4/7ICR switch receptor proliferated and killed better in the presence of IL-4 and showed significantly improved tumor reduction compared to T cells with the CAR alone in NSG mice with subcutaneous pancreatic cancer." (PMID 30804938, 2019). "The Th2 ratio induced by RPMI8266 treated by BCGV and interferon-γ (treated-RPMI8266) cells was only slightly greater than by untreated-tumor cells, but the serum IL-4 level secreted by Th2 cells was markedly higher in treated-RPMI8266 cells group." (PMID 31870332, 2019). "Th2 cells, on the other hand, secrete IL-4, IL-5, IL-6, IL-10, and IL-13, which induce anergy in T cells and enhance the activities of tumor-promoting macrophages." (PMID 31366131, 2019). "Interleukin 4 (IL-4) and Interleukin 13 (IL-13) can induce M2 macrophages, which have anti-inflammatory and tumor-promoting abilities." (PMID 31777603, 2019). "Intraperitoneal administration of bexarotene significantly decreased expressions of CCL22, CXCL5, CXCL10, IL-4, and p19 mRNA in the tumor microenvironment." (PMID 31616630, 2019). "Later, we have shown that transplantation of neural stem/progenitor cells retrovirally engineered to produce IL-4 in C57BL/6 mice with established GBM leads to the survival of most tumor-bearing mice." (PMID 30909395, 2019). "The vast majority of these studies have used mature IL-4-conditioned-DC loaded ex vivo with tumor antigens." (PMID 31611878, 2019). "In contrast, in some types of tumors, the tumor suppressive effects of TAMCs have been reported, mainly by supporting tumor rejection and mediating tumor cell apoptosis via the production of IL-4 and TNF-α." (PMID 30927923, 2019). "IL-4 suppresses the cancer-directed immune surveillance of myeloid cells and increases tumor metastasis in carcinoma." (PMID 30813636, 2019). "At the other extreme, M2-like macrophages, which mimic tumor-associated macrophages (TAMs) present in the tumor microenvironment (TME), can be induced by anti-inflammatory cytokines, such as IL-4 or IL-13." (PMID 31878087, 2019). "Proinflammatory cytokines released by tumor tissue and related inflammatory cells, such as IL-6 and IL-4, can affect Alb synthesis in hepatocytes, leading to reduction of Alb levels." (PMID 31814824, 2019).